KL (klotho)
Diseases named in the same sentence as KL in open-access papers (continued):
Sharing a sentence is not in itself a finding about the gene and the disease.
chronic kidney disease (continued). "Background and Objectives: Soluble alpha Klotho (s.Klotho) is an emerging marker for chronic kidney disease (CKD) prognosis." (PMID 39544340, 2024). "In a mouse model of chronic kidney disease-mineral bone disorder, the release of soluble Klotho alleviates hyperphosphatemia and vascular calcification." (PMID 38385060, 2024). "Another intervention study of patients with chronic kidney disease (N = 79) demonstrated that those with high dietary phosphorus intake had significantly lower levels of Klotho than those with low dietary phosphorus intake." (PMID 37513564, 2023). "Here, we set out to describe the role of FGFR modulator Memo1 in the osteoblast and in bone‐derived FGF23 expression under experimental AKI, based on reports that FGFR‐Klotho signaling is required for FGF23 expression during chronic kidney disease in mice." (PMID 36967231, 2023). "Participants were employed from the NHANES 2007–2016, excluding pregnant, chronic renal insufficiency, and incomplete data of cancer questionnaire and serum Klotho level." (PMID 35841322, 2023). "The decreased expression of Klotho is closely associated with chronic kidney disease (CKD), but reduced Klotho levels are also observed in T2DM subjects with preserved kidney function." (PMID 37686263, 2023). "The overexpression of proinflammatory and inflammatory factors is positively correlated with decreased klotho expression in chronic kidney disease and kidney injury." (PMID 37261217, 2023). "Klotho can be used as an early and sensitive biomarker for kidney illnesses, as well as a potential treatment for both acute kidney injury and chronic kidney disease (CKD)." (PMID 37425590, 2023). "The analysis from the last decade showed that upregulated expression of Klotho is emerging as a promising therapeutic strategy for chronic kidney disease (CKD), acute kidney injury (AKI), and for cardiac hypertrophy, fibrosis and dysfunction." (PMID 37985893, 2023). "Klotho is an anti-aging and anti-calcifying protein, which is reduced in chronic kidney diseases and diabetic mellitus." (PMID 36742073, 2023). "The patients with aging, diabetes and chronic renal diseases often have low plasma or tissue level of Klotho." (PMID 36742073, 2023). "Klotho levels are strongly correlated with chronic kidney disease and renal failure, and individuals with obesity are at a greater risk for developing these conditions." (PMID 37457921, 2023). "By upregulating autophagy, klotho can reduce ischemic kidney injury and mitigate progression to chronic kidney disease." (PMID 37587536, 2023). "Klotho plays an important role as an anti-aging protein in the pathophysiology of multiple aging-related diseases, including atherosclerosis, diabetes, chronic kidney disease, neurological disorders, and cancers." (PMID 37228732, 2023). "Under normal physiological conditions, the kidney is a major regulator that helps in maintaining the klotho level; however, in chronic kidney disease, the Klotho level declines." (PMID 35656176, 2022). "The advantage of higher HEI on S-Klotho was similar across a wide range of subgroups stratified by age, sex, race, chronic kidney disease, smoking and drinking behaviors." (PMID 36712541, 2022). "Clinical and basic research have provided evidence that KL is involved in many human diseases including cardiovascular disease, osteoporosis, cancers, and acute and chronic kidney diseases." (PMID 35992154, 2022). "Evidence shows that a decline in serum Klotho level occurs in early chronic kidney disease (CKD) and continues as CKD progresses." (PMID 36210812, 2022). "Indeed, previous studies found the declined levels of serum klotho are associated with advances in chronic kidney disease (CKD) and cardiovascular diseases." (PMID 36402949, 2022). "Klotho is an anti-ageing protein whose expression is downregulated in chronic kidney disease, but the large size of the protein makes it challenging to deliver therapeutically." (PMID 35064106, 2022).
chronic kidney disease (continued). "In humans, it is well established that plasma Klotho levels decrease with age and in common maladies, such as chronic renal diseases, diabetes and neurodegenerative diseases." (PMID 35903083, 2022). "In rats with chronic renal failure, oral rapamycin treatment also increased klotho, and this improved vascular calcification." (PMID 35903083, 2022). "In humans, Klotho levels decline with age, chronic kidney disease, diabetes, Alzheimer’s disease and other conditions." (PMID 35903083, 2022). "s-Klotho levels are significantly altered in the early stages of chronic kidney disease (CKD), suggesting its utility as an index for early detection of CKD." (PMID 35603960, 2022). "Hypermethylation of klotho promoter decreases the expression of klotho protein in the progress of chronic kidney disease." (PMID 35287592, 2022). "Renal expression of KL as well as circulating KL levels are severely decreased in patients with chronic kidney disease and in experimental animal models of kidney disease including in diabetic db/db mice." (PMID 35992154, 2022). "Klotho proteins have received a great attention in the past few years as possible sensitive and specific markers for chronic kidney disease and CVD." (PMID 35176041, 2022). "On the other hand, reduced levels of KL aggravates renal fibrosis in chronic kidney disease, and overexpression of KL reduces senescence and oxidative stress, and decreases fibrosis and kidney injury in mice in a model of immune complex glomerulonephritis." (PMID 35992154, 2022). "The levels of klotho, a biomarker of chronic kidney disease, began to decline a week after Cd injection, but this molecule was continuously expressed in normal mice with only minor decreases, indicating that Cd caused kidney damage." (PMID 35624155, 2022). "As a result, events that increase FGF23 production will reduce Klotho, such as chronic renal disease." (PMID 35903083, 2022). "Klotho expression in the kidney decreases not only during aging but also in acute kidney injury and chronic kidney disease." (PMID 34737707, 2021). "Further research should examine the effects of both ovariectomy and glucocorticoids on klotho expression, given its role in aging and in chronic kidney disease." (PMID 35011173, 2021). "Related to endothelial dysfunction, one study found that Klotho, a protein expressed by the distal vessels of the kidney, is decreased in chronic kidney disease, leading to abnormal vascular endothelial function and cerebrovascular disease." (PMID 33478332, 2021). "Accordingly, older adults and patients with chronic kidney disease (CKD), which are known states of Klotho deficiency, commonly exhibit declines in musculoskeletal health and physical function." (PMID 36188832, 2021). "Taken together, these findings shed light on the use of engineered EVs from MSCs for Klotho delivery in acute and chronic kidney diseases." (PMID 35056905, 2021). "In 2017, the researchers explored whether HDAC inhibition prevents Klotho loss and mitigates the chronic kidney disease- (CKD-) associated bone disorder in a mouse model of CKD-MBD." (PMID 34326880, 2021). "It is well established that Klotho acts prophylactic and therapeutic in acute renal failure or chronic kidney disease." (PMID 32319182, 2020). "Rats with chronic renal failure had low klotho and FGFR1 mRNA and protein levels in the parathyroid." (PMID 32570711, 2020). "A significantly reduced Klotho was observed in patients with either acute or chronic kidney disease (CKD)." (PMID 32571212, 2020). "Klotho expression occurs predominantly in the kidney and is significantly decreased in patients with chronic kidney disease." (PMID 32545510, 2020). "As Klotho is involved in the kidney’s ability to defend against renal insults, this defect should favor chronic kidney disease by abnormal tissue repair and defective protection against damage." (PMID 32927759, 2020).
chronic kidney disease (continued). "Klotho protein declines in diseased kidney tissue of patients with chronic kidney disease (CKD) and animal models with renal interstitial fibrosis." (PMID 31024315, 2019). "Klotho is involved in various pathologies, such as atherosclerosis, heart failure, hypertension, acute kidney injury, chronic kidney disease, diabetes mellitus, and even cancer." (PMID 31772699, 2019). "Accumulating evidence indicates that administration of exogenous Klotho is a rational strategy for the treatment of acute/chronic kidney diseases." (PMID 31772699, 2019). "We analyzed 2101 participants from KoreaN Cohort Study for Outcome in Patients With Chronic Kidney Disease (KNOW-CKD) cohort who had been measured for serum klotho levels." (PMID 29506503, 2018). "Reduced serum and urinary klotho levels are observed in the early stages of acute kidney injury and chronic kidney disease (CKD), with progressive decline in more advanced stages." (PMID 29590173, 2018). "A previous report showed that klotho decreased apoptosis in renal failure, including acute and chronic kidney disease, and its expression was strongly decreased in kidney injury due to various etiologies that mainly involved inflammation and aging." (PMID 30222592, 2018). "Increase in FGF-23 concentration is accompanied by Klotho reduction as chronic kidney disease (CKD) worsens." (PMID 28130714, 2017). "In cardiomyocytes from rodents with chronic kidney disease, soluble klotho has been reported to inhibit ROS generation through the attenuation of Nox2 and Nox4 expression." (PMID 27696667, 2017). "Several studies have demonstrated that the gene and protein expression levels of klotho are serially declined in chronic renal failure patients and diabetic rats." (PMID 25695625, 2015). "Decreased TM-Klotho, described in experimental chronic kidney disease (CKD), prevents actions of FGF23 and lessens circulating s-Klotho." (PMID 25873958, 2015). "Neuroinflammation and changes in klotho levels associate with chronic kidney disease (CKD) and may play a role in the development of cognitive impairment (CI)." (PMID 25961830, 2015). "Expression and/or excretion of fibroblast growth factor-23 (FGF23) and its co-receptor Klotho are altered in patients with end-stage renal disease." (PMID 25200959, 2014). "Klotho protects against arterial calcification reduces arterial stiffness in chronic kidney disease (CKD), increases endothelial survival." (PMID 24991914, 2014). "It has been reported that the mRNA and protein expression levels of Klotho are severely reduced in the kidneys of patients with chronic renal failure compared to control subjects." (PMID 23431388, 2013). "Experimental studies have revealed that Klotho level decreases in acute and chronic kidney diseases and Klotho has a nephron-protective role." (PMID 24693499, 2013). "Renal KL messenger ribonucleic acid (mRNA) was found to be lower in a 5/6 nephrectomy model and in nephrectomy samples from patients with end-stage renal disease." (PMID 24224012, 2013). "Recently, it has been demonstrated that TNF downregulates Klotho (KL) through the nuclear factor kappa B (NFkB) system in animal models of chronic kidney disease and colitis." (PMID 23634661, 2013). "The purpose of the present study was to characterize the relationship between the soluble Klotho level and renal function in patients with various degrees of chronic kidney disease (CKD)." (PMID 23176706, 2012). "A reduction of Klotho levels in urine has been reported in patients with acute kidney injury and in subjects with chronic kidney disease." (PMID 22121479, 2012). "Studies conducted in humans have reported a reduction of Klotho, both tissue (transmembrane) and soluble forms, in acute and chronic kidney disease." (PMID 22121479, 2012).
chronic kidney disease (continued). "Klotho deficiency has been linked with significantly reduced protection against various kidney pathological phenotypes, including diabetic kidney disease (DKD), which is a major cause of chronic kidney disease leading to end-stage kidney disease." (PMID 40119098, 2025). "Reactivation of endogenous Klotho production or exogenous Klotho supplementation may alleviate renal and cardiac fibrosis, delay the progression of chronic kidney disease, improve mineral metabolism, enhance cardiomyopathy, and reduce vascular calcification." (PMID 41517379, 2025). "Osthole may treat chronic kidney disease by regulating Klotho expression, although its mechanism of action requires further investigation." (PMID 41347159, 2025). "Chronic kidney disease (CKD) is associated with many disturbances in the homeostasis of calcium, phosphate, parathyroid hormone (PTH), calcitriol, fibroblast growth factor 23 (FGF23), and Klotho." (PMID 41303166, 2025). "Moreover, patients with chronic kidney disease (CKD) exhibit significantly reduced Klotho levels accompanied by elevated inflammatory cytokines, including interleukin-6 (IL-6) and tumor necrosis factor-alpha (TNF-α)." (PMID 40519908, 2025). "Therefore, we excluded participants with chronic kidney disease and corrected Klotho with serum creatinine." (PMID 35841322, 2023). "Patients with chronic renal failure have substantially reduced Klotho." (PMID 37759974, 2023). "Thus, both the reduction of soluble Klotho in blood and the decrease of gene expression in PBCCs have been associated with increased CIMT in patients with moderate to severe chronic kidney disease (CKD)." (PMID 37274332, 2023). "Therefore, Klotho deficiency is proposed to be a common feature of kidney diseases and has an important role in their pathogenesis and development, including chronic kidney disease (CKD) and related complications." (PMID 36210812, 2022). "This may be particularly relevant in patients with chronic kidney disease who have decreased Klotho levels in tissues and blood." (PMID 35205271, 2022). "In chronic renal disease of various etiology, as well as diabetes, Klotho production is decreased." (PMID 35903083, 2022). "Vitamin D supplementation also increases Klotho, as shown in children with chronic kidney disease." (PMID 35903083, 2022). "Although research on the functions of klotho in chronic kidney diseases have gained considerable ground in the last decades, much is still unknown of the regulation of its expression, release, and metabolism." (PMID 36434087, 2022). "Levels of serum klotho in humans decrease with aging, and klotho protein in humans has been studied for the association with age-related diseases such as kidney diseases including acute kidney injury (AKI) and chronic kidney disease (CKD), hypertension, metabolic syndrome, and diabetes mellitus." (PMID 35351833, 2022). "In this study, we analysed FGF23, Klotho, 1,25-dihydroxyvitamin D3, 25-hydroxyvitamin D, parathormone, Calcium and Phosphate levels of haemodialysis patients in order to investigate the nature of the mineral metabolism disruption in chronic kidney diseases." (PMID 33776565, 2021). "Importantly, chronic kidney disease, which eventually progresses to cardiovascular disease, is characterized by reduced Klotho levels and FGF23 up-regulation." (PMID 32640692, 2020). "The analyses were performed with data from 1793 patients in whom 24-h urine protein and phosphate, serum phosphate, FGF23, and klotho levels were measured simultaneously, obtained from the KoreaN cohort study for Outcome in patients With Chronic Kidney Disease (KNOW-CKD)." (PMID 32569271, 2020). "Renal dysfunction has been related to Klotho protein, but there are few studies correlating kidney function to KLOTHO polymorphisms in subjects without chronic kidney disease." (PMID 32444684, 2020). "Low levels of KL are present in patients with chronic renal failure." (PMID 32999998, 2020).
chronic kidney disease (continued). "Researchers emphasize that recombinant Klotho may be prophylactic and therapeutic in progression of acute to chronic kidney disease, renal fibrosis and uremic cardiomyopathy." (PMID 32319182, 2020). "The role of emerging factors like FGF-23 and Klotho in cardiovascular risk in both the early and late stages of chronic kidney disease is not entirely understood." (PMID 30934737, 2019). "The prognostic role of Klotho in patients with chronic kidney disease is still controversial." (PMID 31275449, 2019). "In light of these findings, the main pathophysiological consequence of the downregulation of Klotho observed in acute and chronic renal failure may be the induction of renal FGF23 resistance." (PMID 29851418, 2018). "Serum Klotho and IS levels were analyzed in patients with chronic kidney disease." (PMID 30671457, 2018). "A high Klotho protein level may decrease the severity of chronic kidney disease and mineral bone disorder (CKD-MBD) in MHD patients with low BMD." (PMID 29665846, 2018). "Collectively, these advances represent a major step in our understanding of Klotho biology and may have important implications for the pathophysiology of acute and chronic renal failure." (PMID 29851418, 2018). "Klotho, a protein linked to aging, has emerged as a pivotal player in mineral bone metabolism and might explain the relationship between chronic kidney disease (CKD) and cardiovascular disease (CVD)." (PMID 29506503, 2018). "Increased concentration of fibroblast growth factor 23 (FGF-23) and decreased levels of soluble Klotho (sKL) are linked to negative clinical outcomes among patients with chronic kidney disease and acute kidney injury." (PMID 28130714, 2017). "Interestingly, it has been demonstrated that TNF downregulates KL through the transcription nuclear factor kappa B (NFkB) in animal models of chronic kidney disease and colitis." (PMID 23634661, 2013). "Severely reduced production of KL can induce chronic renal failure in the human kidney." (PMID 23741331, 2013). "Clinical studies also showed that a decreased level of serum klotho might be an early biomarker for chronic kidney disease-induced cardiovascular disorder.However, studies on the cardioprotection of klotho are limited." (PMID 24340070, 2013). "However, further long-term prospective studies are required to establish the utility/value of Klotho as an early marker of acute and chronic renal disease." (PMID 22121479, 2012). "The regulation of chronic kidney disease (CKD) by HDAC3 appears to involve the peroxisome PPARγ/Klotho pathway." (PMID 39143689, 2025). "The anti‐arrhythmogenic effect of Klotho related to diastolic Ca2+ leak has also been described in several models of uremic cardiomyopathy, where renal function was severely impaired as a consequence of the development of chronic kidney disease or the induction of acute kidney injury." (PMID 39815421, 2025). "Hyperactivity of these enzymes in conditions like chronic kidney disease (CKD) leads to Klotho promoter hypermethylation, suppressing its expression and worsening kidney dysfunction." (PMID 40004457, 2025). "Therapeutic strategies aimed at enhancing Klotho expression—such as the use of renin-angiotensin system inhibitors, statins, vitamin D receptor agonists and experimental gene therapy are currently being explored in the context of chronic kidney disease and age-related disorders." (PMID 41303567, 2025). "Klotho, an aging-suppressor protein, has been shown to promote cardiovascular and bone health in animal models of chronic kidney disease (CKD)." (PMID 41141519, 2025). "Expression of Klotho decreases gradually during the progression of chronic kidney disease (CKD), while the FGF23 levels increase." (PMID 40165603, 2025). "The FGF23/Klotho axis has a well-established role in the pathogenesis of chronic kidney disease–mineral and bone disorder (CKD-MBD), with FGF23 levels rising in the early stages of CKD." (PMID 41367909, 2025).